HTATSF1 (HIV-1 Tat specific factor 1)
Description:
Component of the 17S U2 SnRNP complex of the spliceosome, a large ribonucleoprotein complex that removes introns from transcribed pre-mRNAs. The 17S U2 SnRNP complex (1) directly participates in early spliceosome assembly and (2) mediates recognition of the intron branch site during pre-mRNA splicing by promoting the selection of the pre-mRNA branch-site adenosine, the nucleophile for the first step of splicing. Within the 17S U2 SnRNP complex, HTATSF1 is required to stabilize the branchpoint-interacting stem loop. HTATSF1 is displaced from the 17S U2 SnRNP complex before the stable addition of the 17S U2 SnRNP complex to the spliceosome, destabilizing the branchpoint-interacting stem loop and allowing to probe intron branch site sequences. Also acts as a regulator of transcriptional elongation, possibly by mediating the reciprocal stimulatory effect of splicing on transcriptional elongation. Involved in double-strand break (DSB) repair via homologous recombination in S-phase by promoting the recruitment of TOPBP1 to DNA damage sites. Mechanistically, HTATSF1 is (1) recruited to DNA damage sites in S-phase via interaction with poly-ADP-ribosylated RPA1 and (2) phosphorylated by CK2, promoting recruitment of TOPBP1, thereby facilitating RAD51 nucleofilaments formation and RPA displacement, followed by homologous recombination. (Microbial infection) In case of infection by HIV-1, it is up-regulated by the HIV-1 proteins NEF and gp120, acts as a cofactor required for the Tat-enhanced transcription of the virus.
Synonyms: Tat-SF1; TATSF1; dJ196E23.2
Tractability: Small molecule: a structure with a bound ligand is known. PROTAC: UniProt records ubiquitination sites on it; ubiquitination databases record sites on it; its protein half-life has been measured.
Gene: Protein-coding gene on chromosome X (136,496,932 to 136,513,181, forward strand). Ensembl gene ENSG00000102241.
Subcellular location: Nucleus; Chromosome
Subcellular location (Human Protein Atlas): Nucleoplasm
Pathways (Reactome):
Metabolism of RNA: mRNA Polyadenylation; mRNA Splicing - Major Pathway
Gene Ontology:
Molecular function: chromatin-protein adaptor activity; poly-ADP-D-ribose modification-dependent protein binding; protein binding; RNA binding; nucleic acid binding
Biological process: double-strand break repair via homologous recombination; mRNA splicing, via spliceosome; protein localization to site of double-strand break; U2-type prespliceosome assembly; chromatin organization
Cellular component: chromosome; nucleoplasm; nucleus; site of double-strand break; U2-type spliceosomal complex; spliceosomal complex; U2 snRNP
Homologues: Orthologues: chimpanzee HTATSF1 (99% identical), macaque HTATSF1 (97% identical), dog HTATSF1 (82% identical), rat Htatsf1 (77% identical), mouse Htatsf1 (77% identical), rabbit HTATSF1 (75% identical), pig HTATSF1 (58% identical), tropical clawed frog htatsf1 (34% identical), zebrafish htatsf1 (33% identical), Drosophila melanogaster barc (23% identical), Caenorhabditis elegans cus-2 (20% identical).
Diseases named in the same sentence as HTATSF1 in open-access papers:
HTATSF1 is named in the same sentence as 13 diseases in open-access papers, as found by Europe PMC text mining. Sharing a sentence is not in itself a finding about the gene and the disease. The quoted sentences say what the papers report.
breast carcinoma (3 papers, 2015 to 2024). "Immunoblotting analysis showed that breast cancer cells expressed higher levels of HTATSF1 and TOPBP1 compared to MCF10A and HMECs, and HTATSF1 pS748 was also upregulated in these cancer cells." (PMID 38762174, 2024). "Similar observations were obtained when examining the level of HTATSF1 pS748 in these breast cancer cells." (PMID 38762174, 2024). "To evaluate the clinical relevance of these mutations and deletions, we first used the CRISPR/Cas9 system to generate a premature stop codon before the coding sequence of HTATSF1 S748 on genomic DNA in breast cancer cells." (PMID 38762174, 2024). "It is likely that in the S-phase of cell cycle, highly expressed HTATSF1 allows actively replicating breast cancer cells to be well-equipped with HTATSF1 pS748-orchestrated CK2–HTATSF1–TOPBP1 axis, thus counteracting replication stress-induced DSBs via HR repair." (PMID 38762174, 2024). "Although the binding affinity of PGK1 and HTATSF1 needs to be further assessed in breast cancer." (PMID 34091600, 2021). "Indeed, HTATSF1/S748A, which does not interact with TOPBP1, could not rescue HTATSF1 depletion–induced repair defects and chemotherapeutic sensitivity in breast cancer cells." (PMID 38762174, 2024). "In contrast to HTATSF1/Wt and HTATSF1/S748D, HTATSF1/S748A mutation could not efficiently rescue HTATSF1 depletion-induced defects, upon cisplatin and irradiation treatment, including TOPBP1 recruitment and RAD51 loading at γH2AX-marked damaged chromatin in EdU-labeled S-phase breast cancer cells." (PMID 38762174, 2024).
lung carcinoma (2 papers, 2021 to 2024). "Dysregulated expression of HTATSF1 has also been reported in lung cancer compared to normal adjacent tissues." (PMID 38762174, 2024). "We then took similar strategies to edit the HTATSF1 gene in human lung carcinoma A549 cells, which carry a higher percentage of truncated mutation and a similar level of HTATSF1 deletion compared to breast tumor." (PMID 38762174, 2024). "Cell survival and xenograft experiments showed that HTATSF1 editing rendered lung cancer cells more sensitive to chemotherapeutic agents and reduced tumor volume or weight." (PMID 38762174, 2024). "Taken together, these results lead us propose that PGK1 coordinates with HTATSF1 to promote lung cancer migration through protein–protein interactions." (PMID 34091600, 2021). "Through a two-way model, we confirmed that PGK1 and HTATSF1 could directly bind in lung cancer cells." (PMID 34091600, 2021). "This evidence supports the hypothesis that the PPI between PGK1 and HTATSF1 may promote lung cancer metastatic ability." (PMID 34091600, 2021). "After IHC scoring, the high level of PGK1 combined with the high level of HTATSF1 staining significantly correlated with a poor overall survival and disease-free survival compared with a low level of PGK1 combined with a low level of HTATSF1 in lung cancer." (PMID 34091600, 2021).
autism (1 paper, 2017). Persistent deficits in social interaction and communication and interaction as well as a markedly restricted repertoire of activity and interest as well as repetitive patterns of behavior. "Of these variants, 4 were found in genes not previously implicated in ASD nor listed in Autism databases (DDX26B, HTATSF1, ITIH6 and PLP1)." (PMID 28720891, 2017).
breast tumors (1 paper, 2024). "Taken together, these results support the argument that a hyperactivated CK2–HTATSF1–TOPBP1 axis confers poor responsiveness of breast tumors to chemotherapeutic agents and that loss of HTATSF1 renders breast tumors more vulnerable to cisplatin treatment." (PMID 38762174, 2024). "Notably, xenograft experiments showed that breast tumors expressing the edited HTATSF1 gene responded more effectively to cisplatin treatment." (PMID 38762174, 2024). "We reported that CK2-catalyzed HTATSF1 pS748 is critically involved in breast tumorigenesis, which raises the possibility of combining chemotherapeutic drugs targeting HTATSF1 pS748 or the HTATSF1–TOPBP1 binding surface for the treatment of HTATSF1–TOPBP1 proficient breast tumors." (PMID 38762174, 2024). "We propose that targeting CK2 or disrupting the molecular interface of HTATSF1–TOPBP1 may be a promising therapeutic strategy for the treatment of CK2–HTATSF1–TOPBP1–proficient breast tumors." (PMID 38762174, 2024). "The hyperactivated CK2–HTATSF1–TOPBP1 axis confers poor responsiveness of breast tumors to chemotherapeutics and may contribute to breast tumorigenesis by coping with endogenous replication stress, although the transcriptional processing activity of HTATSF1 in tumorigenesis cannot be overlooked." (PMID 38762174, 2024). "We then analyzed the level of HTATSF1 pS748, which is a functional readout of CK2 activity and is interpreted by TOPBP1, via immunohistochemistry (IHC) in breast tumor tissue and tumor-adjacent normal breast tissue." (PMID 38762174, 2024). "Here, we identified S748 in the C-terminal acid-rich domain of HTATSF1 as a necessary site for HTATSF1–TOPBP1 interaction and HR repair in breast tumors." (PMID 38762174, 2024). "Notably, disruption of HTATSF1–TOPBP1 binding in CK2–HTATSF1–TOPBP1 proficient tumors leads to DNA damage accumulation, breast tumor suppression, and increased sensitivity to chemotherapy." (PMID 38762174, 2024).
lung adenocarcinoma (1 paper, 2021). A carcinoma that arises from the lung and is characterized by the presence of malignant glandular epithelial cells. "We conclude that even though PGK1 promoted lung adenocarcinoma migration, it relied on the interaction of PGK1 protein–protein binding with HTATSF1 rather on metabolic events." (PMID 34091600, 2021).
prostate carcinoma (1 paper, 2020). A carcinoma that arises from epithelial cells of the prostate gland. "The inferred subset GRN from the PC3 prostate cancer cell line suggests several genes as suppressors of SDHB, such as PNKB, PWP1, PNP, HADH, HTATSF1, and BAZ1B, among which PWP1, HTATSF1, and BAZ1B are transcription regulators." (PMID 33168813, 2020).
tumor (4 papers, 2021 to 2024). "In contrast, deletion mutations of each gene in this axis, which also occur in breast and lung tumor samples, predict higher HR deficiency scores, and tumor cells bearing a loss-of-function mutation of HTATSF1 are vulnerable to poly(ADP-ribose) polymerase inhibitors or platinum drugs." (PMID 38762174, 2024). "The results showed that either HTATSF1 knockdown or cisplatin treatment limited tumor growth, while the combined treatment elicited a synergistic therapeutic effect." (PMID 38762174, 2024). "Quantitation of IHC staining also showed a higher staining percentage and intensity of PGK1/HTATSF1 in the tumor samples than in the normal group." (PMID 34091600, 2021). "Copy number variation analysis showed that CSNK2A1, HTATSF1, and TOPBP1 gain copy number and their amplification is tightly associated with expression, suggesting a possible genomic cooption for the three genes during tumor evolution." (PMID 38762174, 2024). "Next, shRNA-resistant HTATSF1/Wt, HTATSF1/S748A, and HTATSF1/S748D were individually stably transfected into HTATSF1-depleted MDA-MB-231 cells, and the tumor formation of these cancer cells was assessed using a cisplatin-challenged xenograft model." (PMID 38762174, 2024). "The specificity of pS748 antibody was confirmed using xenograft tumor tissue from MDA-MB-231 cells expressing HTATSF1 shRNA and wildtype HTATSF1 (HTATSF1/Wt) or alanine-substituted mutant HTATSF1/S748A." (PMID 38762174, 2024).
cancer (3 papers, 2021 to 2024). A tumor composed of atypical neoplastic, often pleomorphic cells that invade other tissues. "To further extend the clinical significance of our findings, we analyzed the somatic mutation profile of HTATSF1 in tumors using the Catalogue of Somatic Mutations In Cancer and TCGA databases." (PMID 38762174, 2024). "Thereby, it is of interest to understand the significance of HTATSF1–TOPBP1 complex–mediated HR repair during cancer progression and for therapeutic implications." (PMID 38762174, 2024). "In addition, HTATSF1 truncations or mutations, although less common than amplification, increase the sensitivity of breast and lung tumor cells to PARPi and platinum drug, suggesting potential synthetic lethality strategies for HTATSF1-deficient or -mutant cancers." (PMID 38762174, 2024). "In non-small lung cancer, evidence has been reported that PGK1 regulates cancer metastasis by binding to HTATSF1." (PMID 37958393, 2023). "From the results presented in this study, we propose a novel model in which the PGK1 binds to HTATSF1 and exerts functional control of cancer metastasis." (PMID 34091600, 2021).
HTATSF1 also shares sentences with these, for which no sentence is quoted: asthma (1 paper); hearing loss (1); HIV-1 infection (1); pancreatic cancer (1); vitiligo (1).